SNORD114-28 (small nucleolar RNA, C/D box 114-28)
Synonyms: 14q(II-28)
Gene: Small nucleolar RNA gene on chromosome 14 (100,989,130 to 100,989,201, forward strand). Ensembl gene ENSG00000200480.
Gene Ontology:
Biological process: RNA processing
Cellular component: nucleolus
Homologues: Orthologues: chimpanzee SNORD114-28 (100% identical), macaque SNORD114-28 (100% identical). Paralogues in human: SNORD114-25 (94% identical), SNORD114-22 (93% identical), SNORD114-23 (93% identical), SNORD114-9 (93% identical), SNORD114-21 (92% identical), SNORD114-26 (90% identical), SNORD114-15 (89% identical), SNORD114-5 (89% identical), SNORD114-20 (88% identical), SNORD114-29 (85% identical), SNORD114-3 (85% identical), SNORD114-13 (83% identical), and 26 more.